TMEM127 (transmembrane protein 127)
Diseases named in the same sentence as TMEM127 in open-access papers (continued):
Sharing a sentence is not in itself a finding about the gene and the disease.
viral infections (1 paper, 2020). "We confirmed variants with putative driver role of MAP10, MPZL1, RPS6KA1, SETD1B, TAOK2, TMEM127, and TNFRSF1A genes, and of genes linked to viral infections (DDX3X and RSF1) and DNA repair (PAXIP1)." (PMID 32321919, 2020).
tumor (30 papers, 2013 to 2025). "These mutations typically result in a loss of TMEM127 function, leading to aberrant activation of the mTOR signaling pathway and promoting tumor development." (PMID 41357074, 2025). "In contrast, TMEM127 acts as a tumor suppressor, and loss-of-function mutations have been linked primarily to increased mTOR signaling." (PMID 38687678, 2024). "Often multiple tumors are present especially in association with the germline mutations of RET gene, but MAX and TMEM127 mutations are associated with multiplex neoplasms as well." (PMID 35163370, 2022). "More recently, integrative genomic approaches identified germline mutations in two new tumour suppressor genes: TMEM127 and MAX genes which predispose to familial, bilateral, or apparently sporadic PCCs." (PMID 28471419, 2017). "Two alterations of TMEM127 were both frameshift deletions, which may be accompanied by loss of the wildtype allele in tumor DNA, consistent with a classic tumor suppressor gene mode of inactivation." (PMID 35359413, 2022). "Loss-of-function mutations of TMEM127 have been identified in both familial and sporadic PCC, leading to loss of TMEM127 protein or mislocalization to the cytosol in tumor cells." (PMID 38687678, 2024). "Collectively, our findings demonstrate that METTL3a is required for mTOR activation at least partially through m6A-mediated suppression of TMEM127 expression, and this modulation contributes to tumor cell proliferation." (PMID 37589705, 2023). "TMEM127 is a negative regulator of the mTOR pathway and a tumor suppressor located on chromosome 2q1130." (PMID 33037176, 2020). "In this study, we uncover the Tmem127 tumor suppressor as an unsuspected regulator of insulin signaling and lipogenesis." (PMID 31624249, 2019). "Future studies of Tmem127 should integrate its tumor suppressor functions with its role in cellular glucose and insulin homeostasis." (PMID 31624249, 2019). "It includes oncogenes—rearranged during transfection (RET) proto-oncogene and H-ras GTPase proto-oncogene (HRAS)—and several tumor suppressors: neurofibromin 1 (NF1), transmembrane protein 127 (TMEM127), and MYC-associated factor X (MAX)." (PMID 30345003, 2018). "Once mutated, it is mostly located in the cytoplasm, suggesting the localization of TMEM127 to endomembrane pools is important for its tumour suppressor function." (PMID 29166454, 2017). "Taken together, these data suggest that the outcomes of TMEM127 depletion may be cell type as well as tumor type and stage specific, depending on the cell membrane proteomic repertoire." (PMID 38687678, 2024). "Further, TMEM127 depletion may promote oncogenic signaling in tumor initiation and growth, as we observed in PCC, or potentially contribute to alterations in the tumor immune environment in progression of other cancer models." (PMID 38687678, 2024). "Pathogenic variants of TMEM127 result in an increase in the mTOR signal that may promote the occurrence of PCC, and the degree of its activation may be related to tumor invasion and metastasis." (PMID 35163370, 2022). "NEO cells were confirmed by inference of aneuploidy (InferCNV), showing chromosomal loss profiles concordant with SNP-array data (where available) and loss of heterozygosity for PCPG tumor-suppressor driver genes including VHL (chr3p), NF1 (chr17q), TMEM127 (chr2q) and SDHB (chr1p)." (PMID 36271074, 2022). "Transmembrane protein 127 (TMEM127) is a little-known tumor suppressor gene." (PMID 35941331, 2022). "No family history of tumours was reported, and the sequencing results for the TMEM127 gene showed no mutations." (PMID 25425582, 2015). "Specifically, Clusters C1A and C1B, comprising SDHx- and VHL-mutated tumours, respectively, display a pseudohypoxic signature, whereas Cluster C2A, corresponding to RET-, NF1- and TMEM127-mutated tumours, displays activation of the RAS/mitogen-activated protein kinase (MAPK) signaling pathway." (PMID 25625332, 2015).
tumor (continued). "The second cluster group comprises tumours caused by mutations in the neurofibromatosis type 1 (NF1) tumour suppressor gene, the rearranged during transfection (RET) proto-oncogene, the transmembrane protein 127 (TMEM127) gene and the MYC-associated factor X (MAX) gene." (PMID 40540150, 2025). "Although the MAX mutation is classified as type C2, including RET, NF1, TMEM127,H-RAS and ATRX, which belongs to the SWI/SNF family of chromatin remodeling proteins, as their upregulation will activate the PI3K/AKT and RAS/MAPK signaling pathways resulting in tumor formation." (PMID 39279998, 2024). "TMEM127 tumor suppressor gene is a transmembrane protein with unknown coding function." (PMID 35941331, 2022). "Here, through a genome-wide mutant screen of human antigen-presenting cells, we show that the NEDD4 family HECT E3 ubiquitin ligase WWP2 and a tumor-suppressing transmembrane protein of unknown biochemical function, TMEM127, are required for SteD-dependent ubiquitination of mMHCII." (PMID 32526160, 2020). "TMEM127 interacts with an endogenous transmembrane protein, SUSD6, and WWP2 to mediate the reduction of MHCI in tumour cells." (PMID 41135677, 2025).
cancer (10 papers, 2015 to 2024). A tumor composed of atypical neoplastic, often pleomorphic cells that invade other tissues. "In these cancers, we would predict that TMEM127 loss has similar effects on membrane dynamics, membrane protein accumulation, and CCP formation to those seen in our model and that accumulation of other growth factor receptors, such as MET, on the cell surface will lead to transformation." (PMID 38687678, 2024). "Everolimus is an mTOR inhibitor that targets PTEN and TMEM127, and the resultant inhibitory effect is more pronounced in cancers with high METTL3 expression, albeit small molecule inhibitors of METTL3 are currently under investigation." (PMID 36561529, 2022). "It has been reported that TMEM127 acts as an oncogene in various cancers, but its role in OS is unclear." (PMID 35941331, 2022). "After splitting up the tumors according to genotype cluster (i.e. cluster 1: SDHx- and VHL-related PCC/PGL; cluster 2: RET-, NF1-, and TMEM127-related tumors), malignant tumors (n = 24) clustered more often in genotype cluster 1 (P<0.0001), compared to benign tumors (n = 33)." (PMID 25794004, 2015). "Further, we predict that these oncogenes will provide valuable alternative therapeutic targets that have not been previously explored in TMEM127-mutant cancers." (PMID 38687678, 2024).
infection (1 paper, 2020). The state of being infected such as from the introduction of a foreign agent such as serum, vaccine, antigenic substance or organism. "Activation of wild-type MutuDCs by infection with steD mutant Salmonella led to significantly higher surface MHCII levels than DCs that were not exposed to bacteria, and these levels were unaffected by the absence of either Wwp2 or Tmem127." (PMID 32526160, 2020).
TMEM127 also shares sentences with these, for which no sentence is quoted: breast carcinoma (3 papers); head and neck paraganglioma (3); adrenocortical adenoma (1); benign tumors (1); colon cancer (1); diabetes (1); endocrine tumors (1); Hepatic steatosis (1); hereditary leiomyomatosis and renal cell cancer (1); hyperparathyroidism (1); kidney carcinoma (1); medullary thyroid cancer (1); mesothelioma (1); metabolic disorders (1); multiple endocrine neoplasia (1); ovarian carcinoma (1); pancreatic cancer (1); pheochromocytoma-paraganglioma (1); prostate carcinoma (1); sarcoma (1); tumor predisposition syndrome (1); tumour of the adrenal gland (1).